RNU6-547P (RNA, U6 small nuclear 547, pseudogene)
Gene: Small nuclear RNA gene on chromosome 3 (172,703,124 to 172,703,225, forward strand). Ensembl gene ENSG00000252082.
Homologues: Orthologues: chimpanzee U6 (100% identical), macaque U6 (89% identical), pig U6 (80% identical), mouse Gm22070 (76% identical), pig U6 (75% identical), guinea pig U6 (72% identical). Paralogues in human: RNU6-21P (83% identical), RNU6-140P (81% identical), RNU6-214P (81% identical), RNU6-268P (81% identical), RNU6-333P (80% identical), RNU6-33P (80% identical), RNU6-42P (80% identical), RNU6-774P (80% identical), RNU6-80P (80% identical), RNU6-822P (80% identical), RNU6-86P (80% identical), RNU6-1 (79% identical), and 1286 more.